ZDHHC6 (zDHHC palmitoyltransferase 6)
Description:
Endoplasmic reticulum palmitoyl acyltransferase that mediates palmitoylation of proteins such as AMFR, CALX, ITPR1 and TFRC. Palmitoylates calnexin (CALX), which is required for its association with the ribosome-translocon complex and efficient folding of glycosylated proteins. Mediates palmitoylation of AMFR, promoting AMFR distribution to the peripheral endoplasmic reticulum. Together with SELENOK, palmitoylates ITPR1 in immune cells, leading to regulate ITPR1 stability and function. Stearoyltransferase that mediates stearoylation of TFRC to inhibit TFRC-mediated activation of the JNK pathway and mitochondrial fragmentation.
Synonyms: DHHC-6; ZNF376; FLJ21952; DHHC6
Tractability: Antibody: UniProt predicts a signal peptide or a membrane-spanning region. PROTAC: ubiquitination databases record sites on it; its protein half-life has been measured.
Gene: Protein-coding gene on chromosome 10 (112,424,428 to 112,447,631, reverse strand). Ensembl gene ENSG00000023041.
Subcellular location: Endoplasmic reticulum membrane
Gene Ontology:
Molecular function: palmitoyltransferase activity; protein binding; protein-cysteine S-stearoyltransferase activity; protein-cysteine S-palmitoyltransferase activity
Biological process: intracellular signal transduction; protein targeting to membrane
Cellular component: endoplasmic reticulum; endoplasmic reticulum membrane
Genetic constraint (gnomAD): Loss-of-function variants: 28 observed, 50.93 expected, observed/expected ratio (o/e) 0.55, 90% interval 0.41 to 0.75. The upper end of that interval is the gene's LOEUF score, 0.75, which puts it in group 3 of 6, group 1 being the genes least tolerant of losing a copy. Missense variants: 392 observed, 471.83 expected, observed/expected ratio (o/e) 0.83, 90% interval 0.76 to 0.9. Synonymous variants: 121 observed, 148.83 expected, observed/expected ratio (o/e) 0.81, 90% interval 0.7 to 0.94.
Homologues: Orthologues: chimpanzee ZDHHC6 (100% identical), macaque ZDHHC6 (99% identical), rabbit ZDHHC6 (96% identical), dog ZDHHC6 (96% identical), guinea pig ZDHHC6 (94% identical), mouse Zdhhc6 (93% identical), pig ZDHHC6 (89% identical), rat Zdhhc6 (88% identical), tropical clawed frog zdhhc6 (76% identical), zebrafish zdhhc6 (74% identical), Drosophila melanogaster CG5196 (38% identical), Drosophila melanogaster CG4483 (37% identical), and 1 more. Paralogues in human: ZDHHC3 (20% identical), ZDHHC7 (20% identical), ZDHHC1 (16% identical), ZDHHC2 (15% identical), ZDHHC20 (15% identical), ZDHHC21 (15% identical), ZDHHC14 (15% identical), ZDHHC15 (15% identical), ZDHHC4 (13% identical), ZDHHC12 (13% identical), ZDHHC23 (13% identical), ZDHHC9 (12% identical), and 5 more.
Diseases named in the same sentence as ZDHHC6 in open-access papers:
ZDHHC6 is named in the same sentence as 20 diseases in open-access papers, as found by Europe PMC text mining. Sharing a sentence is not in itself a finding about the gene and the disease. The quoted sentences say what the papers report.
colitis (2 papers, 2024 to 2025). Inflammation of the colon. "ZDHHC6 levels are significantly elevated in the colonic tissues of patients with clinical IBD and correlate with diagnostic indicators of colitis (ESR, CRP, ALB)." (PMID 40959086, 2025). "In addition, we examined the potential involvement of ZDHHC6 expression in colitis and the advancement of colorectal cancer (CRC) related with colitis, by analysing the intersection of ZDHHC6 in many datasets." (PMID 39148124, 2024).
Hearing impairment (2 papers, 2023). A decreased magnitude of the sensory perception of sound. "ZDHHC6 is a palmitoyltransferase located in the ER, and defects in palmitoylation have been linked to hearing impairment." (PMID 37163093, 2023).
inflammatory bowel disease (2 papers, 2024 to 2025). A spectrum of small and large bowel inflammatory diseases of unknown etiology. "The results suggest a link between inflammatory bowel disease (IBD) and the concentrations of ZDHHC6 in the tissue of the colon." (PMID 39148124, 2024). "Significantly, we also verified a negative correlation between the levels of albumin (ALB) in the bloodstream, a potential indicator of inflammatory bowel disease (IBD), and the levels of ZDHHC6 in the colon." (PMID 39148124, 2024).
renal fibrosis (2 papers, 2023 to 2025). A final common manifestation of a wide variety of chronic kidney diseases characterized by glomerulosclerosis and tubulointerstitial fibrosis. "We found that ZDHHC6, ZDHHC9, and ZDHHC18 could catalyze HRAS palmitoylation but that the expression of ZDHHC6 and ZDHHC9 was downregulated during renal fibrosis." (PMID 39913299, 2025). "However, the other PATs, such as ZDHHC6 (preferentially expressed in podocytes) and ZDHHC1, 2, 5 (up-regulated in the fibrotic kidneys), may also contribute to renal fibrosis by regulating palmitoylation of different substrates in various cell types." (PMID 37865665, 2023).
acute myeloid leukemia (1 paper, 2025). Acute myeloid leukemia (AML) is a group of neoplasms arising from precursor cells committed to the myeloid cell-line differentiation. "Additionally, acute myeloid leukemia (AML) cells uptake exogenous palmitate via CD36, activating ZDHHC6-mediated MYD88 palmitoylation to potentiate the TLR4-LYN-MYD88-NF-κB signaling axis." (PMID 40977744, 2025).
breast carcinoma (1 paper, 2025). "Breast cancer MCF-7 cells treated with 30 μM ART or ART-yne (24 h) identified zDHHC6 as a co-interacting partner; as a result, the palmitoylation status of zDHHC6 substrates was altered including H-Ras." (PMID 40004137, 2025).
colon cancer (1 paper, 2024). "ZDHHC6’s role in colon cancer lipid metabolism underscores a multifaceted regulatory mechanism that supports tumor growth and survival." (PMID 39148124, 2024). "Future research should focus on elucidating these mechanisms and exploring the therapeutic potential of ZDHHC6 inhibition in colon cancer treatment." (PMID 39148124, 2024). "We demonstrated that ZDHHC6 promotes the synthesis of fresh fatty acids and the formation of tumors by palmitoylating and stabilizing PPARγ in colon cancer." (PMID 39148124, 2024). "In addition, the analysis of proteins revealed that both human CRC tumour tissues and CRC-related cell lines (SNU-C2A, SW48, HT-29, LS1034, HCT116, and Caco-2) as well as mouse-associated colon cancer cell lines (CT26, MC38, CMT93, and MC26) exhibited elevated levels of ZDHHC6 expression." (PMID 39148124, 2024). "The findings confirmed that the lack of ZDHHC6 played a role in inhibiting the growth of colon cancer cells and the process of EMT." (PMID 39148124, 2024).
colorectal cancer (1 paper, 2024). A primary or metastatic malignant neoplasm that affects the colon or rectum. "We noted a substantial increase in the expression of several fatty acids and triglycerides in the colorectal cancer cells that were overexpressing ZDHHC6." (PMID 39148124, 2024). "Nevertheless, our findings indicate that ZDHHC6 facilitates the production of fatty acids from scratch in colorectal cancer (CRC)." (PMID 39148124, 2024). "Subsequently, we assessed the predictive significance of ZDHHC6 and PPARγ in these datasets of colorectal cancer tissue microarrays (TMA)." (PMID 39148124, 2024). "The results demonstrate that increased expression of ZDHHC6 can stimulate the production of fatty acids in living organisms by activating PPARγ, hence promoting the advancement of colorectal cancer." (PMID 39148124, 2024). "Consistent with our previous findings, we conducted additional experiments to specifically determine the function of ZDHHC6 in colorectal cancer (CRC)." (PMID 39148124, 2024). "To explore the impact of ZDHHC6 on lipid accumulation in colorectal cancer (CRC), we conducted high-throughput RNA sequencing analysis to examine the possible effects of ZDHHC6 on key enzymes involved in fatty acid synthesis in CRC cells." (PMID 39148124, 2024). "Individuals exhibiting characteristics of colorectal cancer (CRC) demonstrated elevated levels of ZDHHC6 protein content in comparison to those in the Crohn’s disease (CD), ulcerative colitis (UC), and healthy control (HC) groups." (PMID 39148124, 2024). "To investigate the role of ZDHHC6 in colorectal cancer (CRC) cells in living organisms, we implanted ZDHHC6-deficient HCT116 cells and ZDHHC6-overexpressing HCT116 cells under nude mice." (PMID 39148124, 2024). "Together, we discovered a previously unknown harmful connection between ZDHHC6 and the variables that regulate the production of fatty acids and the balance of lipid oxidation, specifically related to PPARγ, in patients with colorectal cancer." (PMID 39148124, 2024). "Furthermore, we have discovered a distinct variation in the expression of ZDHHC6 between colorectal cancer (CRC) and normal tissues." (PMID 39148124, 2024). "The purpose of this investigation was to determine whether ZDHHC6 interacts with PPARγ in additional colorectal cancer cells." (PMID 39148124, 2024). "Furthermore, our findings reveals that ZDHHC6 actively stimulates the production of fatty acids and plays a role in the development of colorectal cancer." (PMID 39148124, 2024). "The results of our study offer a potential approach to specifically inhibit the production of fatty acids, which could have therapeutic advantages for individuals with elevated ZDHHC6 levels in colorectal cancer." (PMID 39148124, 2024). "Furthermore, our current study supports the notion that ZDHHC6 may play a role in the development of colorectal cancer (CRC) pathogenesis." (PMID 39148124, 2024). "The studies presented above unambiguously demonstrated that ZDHHC6 is a significant palmitoyltransferase that plays a role in the occurrence of palmitoylated PPARγ, and the activity of this enzyme was found to have a favorable correlation with the progression of colorectal cancer." (PMID 39148124, 2024). "Hence, we examined potential processes that could contribute to the overexpression of ZDHHC6 in colorectal cancer (CRC)." (PMID 39148124, 2024). "Collectively, these findings suggest that ZDHHC6 enhances the accumulation of lipid molecules by upregulating the expression of ACC and ACLY in colorectal cancer." (PMID 39148124, 2024). "Considering the significant impact of ZDHHC6 on the advancement of colorectal cancer (CRC) and its probable involvement in the metabolic processes of tumours, we further examined the influence of ZDHHC6 on the molecular metabolism of CRC." (PMID 39148124, 2024).
colorectal cancer (continued). "Colon samples obtained from persons diagnosed with Crohn’s disease (CD), ulcerative colitis (UC), and colorectal cancer (CRC), as well as from healthy donors (HC), exhibited markedly elevated levels of ZDHHC6 protein compared to the healthy individuals in the control group." (PMID 39148124, 2024). "Furthermore, patients who have colorectal cancer (CRC) and exhibit high expression levels of both ZDHHC6 and PPARγ tend to have an unfavorable prognosis and lower overall survival rates." (PMID 39148124, 2024). "In addition to the substantial rise in ZDHHC6 observed in the TCGA dataset and the ICGC database, In order to confirm the increased expression of ZDHHC6 in colorectal cancer (CRC), we obtained 73 pairs of CRC samples and their matching adjacent samples." (PMID 39148124, 2024).
cancer (4 papers, 2022 to 2025). A tumor composed of atypical neoplastic, often pleomorphic cells that invade other tissues. "There were significantly more biological processes associated with cancer growth and metabolic reprogramming in the group with high ZDHHC6 expression on a regular basis." (PMID 39148124, 2024). "Prior research has shown the varied impacts of ZDHHC6 on biological mechanisms linked to the advancement of cancer." (PMID 39148124, 2024). "However, we have observed a significant reduction in the cancer-causing effects when the expression of ZDHHC6 is inhibited in in vivo trials." (PMID 39148124, 2024). "ZDHHC6, a significant palmitoyltransferase, has been identified as a cancer signature gene and has high expression in various types of cancer." (PMID 39148124, 2024). "ZDHHC6 plays a crucial function in cancer by exerting its impact on the growth and viability of cells." (PMID 39148124, 2024). "In addition, ZDHHC6 has the ability to regulate metastasis, which is a significant factor in cancer-related fatalities." (PMID 39148124, 2024). "ZDHHC6 primarily functions as an oncoprotein by increasing AEG-1 palmitoylation, which in turn activates or stabilizes transcription factors involved in cancer progression." (PMID 39148124, 2024).
tumor (3 papers, 2022 to 2024). "The Pearson multiple correlation and multiple linear regression analyses revealed a significant association between the levels of ZDHHC6 protein and various tumour markers, including CA125, CA50, CA724, CA199, CEA, CA242, CK-BB, and HCG." (PMID 39148124, 2024). "Our investigation revealed that specifically reducing the activity of ACLY significantly suppressed the promotion of tumor growth and the enhancement of fatty acid production induced by overexpression of ZDHHC6." (PMID 39148124, 2024). "This is consistent with our findings, as demonstrated by the transwell analysis, which showed a significant decrease in the invasion and migration of tumor cells when ZDHHC6 was silenced, compared to the control group." (PMID 39148124, 2024). "Accordingly, suppressing the level of AEG-1 palmitoylation by the deletion of Zdhhc6 reproduces the enhanced tumor-progression phenotype in DEN-induced HCC mouse model." (PMID 36276642, 2022). "However, HCT116 cells that were simultaneously overexpressed with ZDHHC6 and co-transfected with shPPARγ or PPARγ C313S mutants exhibited lower rates of tumor growth." (PMID 39148124, 2024). "In addition, ZDHHC6 has a role in promoting cell proliferation by controlling the flow of calcium ions through selenoprotein K during the development of tumor growth." (PMID 39148124, 2024). "ZDHHC6 acts as an oncogenic protein in the process of tumor formation." (PMID 39148124, 2024). "Moreover, we collected six pairs of clinical HCC tumor and adjacent normal tissues, and consistently, these results confirmed a decreased level of zDHHC6 in HCC samples." (PMID 36276642, 2022). "For example, ZDHHC6-mediated palmitoylation of AEG-1 enhances proteasomal degradation of AEG-1, suppressing HCC tumor growth." (PMID 37828054, 2023). "In addition, mice that had been implanted with HCT116 cells in which ZDHHC6 had been suppressed and PPAR had been overexpressed exhibited higher rates of tumor formation compared to the CRC cells that had only been transfected with shZDHHC6." (PMID 39148124, 2024). "Furthermore, in vivo experiments demonstrated that inhibiting ZDHHC6 effectively decreased the rates of tumor growth and the weights of tumors in mice that had been implanted with the SNU-C2A tumor models." (PMID 39148124, 2024). "In addition, the mice carrying the ZDHHC6 knockdown and mutant PPARγ C313S HCT116 cells exhibited significantly suppressed tumor formation compared to the mice with shControl." (PMID 39148124, 2024). "Conversely, the tumours originating from ZDHHC6-deleted HCT116 cells exhibited a notable reduction in several lipid metabolites, such as fatty acids, when compared to tumours formed from control cells." (PMID 39148124, 2024).
cardiovascular disease (1 paper, 2021). "Calnexin is an ER chaperone that has been implicated in cardiomyocyte viability and in ER stress, a prominent clinical feature of cardiovascular disease, while ITPR1 mediates the influx and release of intracellular Ca2+ and is regulated by the palmitoylation cascade of ZDHHC16/ZDHHC6." (PMID 34252155, 2021).
ZDHHC6 also shares sentences with these, for which no sentence is quoted: deafness (2 papers); atherosclerosis (1); Chronic colitis (1); Crohn disease (1); hepatocellular carcinoma (1); intestinal infections (1); pancreatic cancer (1); Stroke (1); ulcerative colitis (1).